NXPE1 (neurexophilin and PC-esterase domain family member 1)
Synonyms: FAM55A; MGC34290
Tractability: Antibody: UniProt places it where antibodies can reach, with medium confidence; UniProt predicts a signal peptide or a membrane-spanning region; its Gene Ontology location is reachable by antibodies, with medium confidence.
Gene: Protein-coding gene on chromosome 11 (114,518,842 to 114,559,888, reverse strand). Ensembl gene ENSG00000095110.
Subcellular location: Secreted
Gene Ontology:
Molecular function: N-acetylneuraminate 9-O-acetyltransferase activity; protein binding
Cellular component: Golgi apparatus; extracellular region
Genetic constraint (gnomAD): Loss-of-function variants: 25 observed, 27.58 expected, observed/expected ratio (o/e) 0.91, 90% interval 0.66 to 1.27. The upper end of that interval is the gene's LOEUF score, 1.27, which puts it in group 5 of 6, group 1 being the genes least tolerant of losing a copy. Missense variants: 590 observed, 617.77 expected, observed/expected ratio (o/e) 0.96, 90% interval 0.89 to 1.02. Synonymous variants: 209 observed, 222.48 expected, observed/expected ratio (o/e) 0.94, 90% interval 0.84 to 1.05.
Homologues: Orthologues: chimpanzee NXPE1 (98% identical), rabbit NXPE1 (73% identical). Paralogues in human: NXPE2 (70% identical), NXPE4 (68% identical), NXPE3 (28% identical).
Diseases named in the same sentence as NXPE1 in open-access papers:
NXPE1 is named in the same sentence as 4 diseases in open-access papers, as found by Europe PMC text mining. Sharing a sentence is not in itself a finding about the gene and the disease. The quoted sentences say what the papers report.
inflammatory bowel disease (1 paper, 2025). A spectrum of small and large bowel inflammatory diseases of unknown etiology. "Genome-wide association studies have shown that the genomic region containing NXPE1 is linked to inflammatory bowel disease, as well as a non-significant trend for metastatic colorectal cancer risk." (PMID 40425538, 2025).
tumor (1 paper, 2018). "Consistent with the bioinformatics predictions, MUC12 and NXPE1 presented a sequentially descending trend in expression with tumor progression, and TIMP1 presented a sequentially ascending trend." (PMID 29659199, 2018). "HEPACAM2, ITLN1, LGALS2, MUC12, and NXPE1 presented a sequentially descending trend in expression with tumor progression." (PMID 29659199, 2018).
NXPE1 also shares sentences with these, for which no sentence is quoted: cancer (1 paper); metastatic colorectal cancer (1).